RNU7-102P (RNA, U7 small nuclear 102 pseudogene)
Gene: Small nuclear RNA gene on chromosome 8 (69,110,513 to 69,110,574, reverse strand). Ensembl gene ENSG00000238808.
Homologues: Orthologues: chimpanzee U7 (100% identical), macaque U7 (82% identical). Paralogues in human: RNU7-48P (84% identical), RNU7-24P (82% identical), RNU7-120P (81% identical), RNU7-88P (81% identical), RNU7-130P (79% identical), RNU7-37P (79% identical), RNU7-40P (79% identical), RNU7-70P (79% identical), RNU7-97P (79% identical), RNU7-129P (77% identical), RNU7-12P (77% identical), RNU7-136P (77% identical), and 142 more.